KLK6 (kallikrein related peptidase 6)
Diseases named in the same sentence as KLK6 in open-access papers (continued):
Sharing a sentence is not in itself a finding about the gene and the disease.
cancer (continued). "KLK6 is aberrantly expressed in several solid tumors and regulates cancer development, metastatic progression, and drug resistance." (PMID 36552865, 2022). "The treatment with the TNF-α neutralizing antibody in the CM of WT BMDMs and KLK6-overexpressing RAW 264.7 cells suppressed CXCL1 production from cancer cells." (PMID 36552865, 2022). "Our findings suggest that KLK6 functions as an important molecular link between macrophages and cancer cells during malignant progression." (PMID 36552865, 2022). "Several studies have suggested that the KLK6 transcript and protein are highly expressed in various human cancers including breast, lung, pancreatic, colorectal, gastric, and ovarian cancers." (PMID 36552865, 2022). "Our findings suggest that KLK6 functions as an important molecular link between macrophages and cancer cells during malignant progression, thereby providing opportunities for therapeutic intervention." (PMID 36552865, 2022). "Using the KLK-CANMAP, a tool that includes several other cancer datasets, we again found the KLK6, KLK7, KLK8 and KLK10 cluster, with the exception of KLK11, which was upregulated in PDAC compared to normal pancreas tissues." (PMID 34439122, 2021). "KLK6 interacts with other secreted factors as part of proteolytic networks, which are dysregulated in cancer and other diseases." (PMID 34439122, 2021). "The human kallikrein 6 (KLK6) gene encodes a member of the KLK-related peptidase family, also known as the human cancer biomarker family, which comprises at least 15 members and is located on chromosome 19q13.3–13.4." (PMID 34915845, 2021). "Aberrant expression of KLK6 has been found in different cancers and neurodegenerative diseases, and KLK6 is currently studied as a potential target in these pathologies." (PMID 31675166, 2020). "Accumulating evidence indicates that microRNAs (miRNAs) are involved in post-transcriptional regulation of several KLK genes in cancer, e.g. KLK6 and KLK10." (PMID 32028882, 2020). "As a proteolytic enzyme, KLK6 can contribute to the invasive phenotype of cancer cells via degradation of extracellular matrix proteins, such as collagen, fibronectin, laminin, fibrinogen and activation of matrix metalloproteinases." (PMID 31692974, 2019). "In basal‐like cancer, there was a positive correlation of KLK6 and S100A11 and S100A2, in accordance with our findings." (PMID 30980596, 2019). "Aberrant KLK6 expression is a common feature for many human cancers, and numerous studies evaluated KLK6 as a promising biomarker for early diagnosis or unfavorable prognosis." (PMID 28671620, 2017). "KLK6 mRNA was approximately 6-fold higher in cancer tissues than in normal tissues and in NCI-N87 and SNU-620 cells than in the other cell lines." (PMID 27863404, 2016). "Many of these genes and their encoded proteins are involved in carcinogenesis and are considered novel potential cancer biomarkers, such as the proteases prostate specific antigen, kallikrein-related peptidase 6 (KLK6), or the apoptosis regulator bax-δ." (PMID 26305455, 2015). "The score, encompassing the clinical factors of ascitic fluid volume and nuclear grading, plus the cancer biomarkers KLK6 and KLK13, is designed to predict the efficiency of the intra-abdominal debulking procedure." (PMID 25436002, 2015). "Deregulation of KLK6 expression occurs in neurodegenerative and skin disorders, and is a common event in human cancer." (PMID 25990935, 2015). "In a previous study, we established the OVSCORE, an algorithm to predict surgical outcome, based on the clinical factors of nuclear grading and ascitic fluid volume, plus the cancer biomarkers, kallikrein-related peptidases (KLKs), KLK6 and KLK13." (PMID 25436002, 2015). "This score encompasses the clinically relevant factors of ascitic fluid volume and nuclear grading, plus two novel cancer biomarkers, the serine proteases KLK6 and KLK13." (PMID 25436002, 2015).
cancer (continued). "The level of KLK6 was significantly increased in the plasma samples from the cancer cohort compared to the benign and healthy cohorts and moreover showed a slight decrease in the postoperative plasma samples in comparison to the preoperative plasma samples." (PMID 24669031, 2014). "KLK6 has been shown to cleave components of the extracellular matrix (ECM), therefore it was concluded that KLK6 promotes cancer invasion and metastasis." (PMID 23216878, 2012). "Compared to patients with low KLK6, a significantly larger proportion of patients with high KLK6 had invasive cancer (P=0.002) and late stage cancers (P=0.001)." (PMID 19707197, 2009). "The results indicate that this effect is most likely mediated by the interaction of KLK6 with factors of the extracellular matrix and the enhancement of cancer cell motility by KLK10." (PMID 18854834, 2008). "Beyond cancer, KLK6 has been explored as a biomarker in renal impairment." (PMID 40428321, 2025). "Klk6 is the mouse ortholog of human KLK6 that belongs to a large family of kallikrein-related peptidases, representing secreted serine proteinases with diverse expression patterns and functions in cell physiology, including cancer." (PMID 39594797, 2024). "Therefore, our results suggest that inhibition of the KLK6/PAR1 axis would provide a potential therapeutic strategy for cancer." (PMID 36552865, 2022). "Next, we isolated BMDMs from WT or KLK6−/− mice to investigate whether macrophages affect KLK6-mediated CXCL1 expression in cancer cells." (PMID 36552865, 2022). "Based on TCGA database analysis, KLK6 is significantly upregulated in 16 cancer types." (PMID 36193495, 2022). "We then tested the effect of a kallikrein-related peptidase 6 inhibitor on cancer cell functions." (PMID 34439122, 2021). "Here we found that KLK6 high tumors carry mutations in two longest genes in the human genome, i.e., TTN, a structural protein in striated muscles and MUC16, which encodes the cancer antigen CA-125." (PMID 34065672, 2021). "KLK6 was shown to be involved in many cancers’ formation and progression." (PMID 34359689, 2021). "Comparison between patients categorized according to biomarker expression, using formula A, i.e. [KLK6/CEACAM5 + SLC35D3/CEACAM5 + POSTN/18S rRNA -MUC2/CEACAM5], with regard to risk for recurrence of disease and cancer death and observed recurrence 3 and 5 years after curative surgery." (PMID 32049988, 2020). "KLK6 was discovered and cloned by several independent laboratories and later was reported to be highly expressed during inflammation, as well as in many cancers and cancer cell lines." (PMID 27283773, 2016). "KLK6 along with 10 and 11 and 13 are emerging biomarkers for ovarian and cancer." (PMID 25505737, 2014). "Potential regulatory interaction between KLK6 and proteases of the thrombostasis axis could have a large impact in various human diseases, including neurodegeneration and cancer." (PMID 23216878, 2012). "With the involvement in these biological functions, the overexpression of KLK6 in ovarian cancer suggests it may be involved in promoting cancer invasion and metastasis." (PMID 19707197, 2009). "KLK6 might exert this effect by the degradation of matrix proteins and thereby the augmentation of cancer cell motility and proliferation." (PMID 18854834, 2008). "However, this induction was markedly lower in cancer cells treated with the CM of KLK6−/− BMDMs." (PMID 36552865, 2022). "In our study, KLK6 was a risk factor for low muscle mass, notably, in participants without cancer." (PMID 34151535, 2021). "B1R may have a potential target receptor for KLK6 secretion in cancer." (PMID 27863404, 2016). "Most of these cancers, such as glioma, ovarian, breast, uterine, pancreatic, colorectal, gastric, skin, urinary bladder, lung and salivary gland tumors, were characterized by a strong increase of KLK6 transcript and protein levels as compared to normal tissues." (PMID 25990935, 2015).
cancer (continued). "HSP90α KO cells were crucial in determining the complex interplay between extracellular proteins, leading to the discovery of a unique role for an extracellular serine protease, KLK6, in MMP-2 regulation and cell motility in cancer." (PMID 41597241, 2026). "It is known that different cancer signaling pathways, such as TGF-β, mutant APC, and an enzymatically active KLK6, lead to the activation of the ERK1/2 MAP kinase during intestinal tumorigenesis." (PMID 39594797, 2024). "Among these model genes (FLNC, KLK6, PTGIS, PLAAT1 and GLYATL2), FLNC is an actin-binding protein that regulates the actin cytoskeleton in cells and is involved in cancer metastasis." (PMID 38363409, 2024). "Our data show strong evidence that proves that increasing the expression level of miR-378 in cells by EPA induces the PGC-1β gene, which possibly affects KLK2, KLK4, KLK6, and KLK14 gene expression in cancer cells." (PMID 35681793, 2022). "The kallikrein-related peptidase Kallikrein 6 (KLK6) is overexpressed in CRC and contributes to cancer cell invasion and metastasis." (PMID 34065672, 2021). "Therefore, KLK6 could trigger glycolytic flux in cancer cells (Andreic and Legiša, 2018)." (PMID 30980596, 2019). "The mRNA expression status of the KLK5, KLK6, KLK7, KLK8 and KLK9 has been extensively studied in cancer." (PMID 29229980, 2017). "Ingenuity analysis identified a group of 7 genes (BEX1, FBLN1, FGD3, HBEGF, KLK3, KLK6, and WNT5B) related to cancer, cellular function and maintenance, cellular growth, invasion, as well as proliferation with P < 0.001-0.05." (PMID 21134280, 2010). "Expression levels of both KLK6 and KLK13 mRNA were significantly increased in invasive cancers relative to normal ovaries (P=0.002 and 0.039 respectively)." (PMID 19707197, 2009). "This is in agreement with our unpublished data showing overexpression of several kallikreins (KLK6, KLK7, KLK10) on the mRNA level of cancer samples as compared with their paired normal colon mucosa." (PMID 19367279, 2009). "KLK6 and TGF-β are both involved in complex cellular processes, including cancer progression." (PMID 39594797, 2024). "Several genes that were highly expressed in Cluster 3 were well known to be preferentially expressed in normal oligodendrocytes, including CLDN11, MBP, PLP1, and KLK6, indicating that these cells are not cancer cells." (PMID 27368803, 2016). "KLK6-specifc tags were also detectable in three out of eight normal libraries with high density (average 270 tpm) and in only two cancer libraries (out of 24) with low average expression level (15 tpm)." (PMID 14710225, 2004). "In survival analysis, we confirmed one kallikrein (KLK6) that had previously been associated with poor survival and identified one kallikrein (KLK7) that previously had not been implicated in prognosis of this cancer." (PMID 29707153, 2018). "The role(s) of KLK6 in the progression of human malignancies are not clear and they may vary with the type of cancer and KLK6 levels of expression." (PMID 23216878, 2012). "However, KLK6 silencing did not affect macrophage-induced CXCL2 production in cancer cells." (PMID 36552865, 2022). "The high KLK6 mRNA level was reported in non-malignant adenomatous tissue of CRC patients when compared to the KLK6 mRNA levels in the adjacent normal mucosa and malignant tumors." (PMID 39594797, 2024). "To determine the effect of TNF-α on macrophage-mediated CXCL1 production in cancer cells, we treated B16F10 cells with the CM of mock-transfected or KLK6-transfected RAW 264.7 cells in the presence or absence of the TNF-α neutralizing antibody." (PMID 36552865, 2022).
cancer (continued). "This demonstrated that EPA could significantly induce PCa cell death by down-regulating the KLK2, KLK4, KLK6, and KLK14 genes in PCa cells, then triggering apoptosis in the cancer cells; however, a similar mechanism did not affect the normal cells." (PMID 35681793, 2022).
neurodegenerative disease (8 papers, 2016 to 2025). A disorder of the central nervous system characterized by gradual and progressive loss of neural tissue and neurologic function. "In neurodegenerative diseases such as multiple sclerosis, Alzheimer's15 and Parkinson's,16 as well as spinal cord injury, aberrant levels of KLK6 have been reported." (PMID 31675166, 2020). "The levels of other proteins in the CSF have also shown promise as potential biomarkers for neurodegenerative disease progression, with the levels of neurogranin (a post-synaptic marker) and kallikrein-related peptidase-6 (KLK-6) levels correlating with AD severity and advanced age respectively." (PMID 40307257, 2025). "Kallikrein-6 (KLK6) is an enzyme with a major role in neuroinflammatory and neurodegenerative diseases." (PMID 35458486, 2022). "KLK6 and CSTB have been suggested as biomarkers reflecting cardiovascular disease and neurodegenerative diseases." (PMID 34312731, 2021).
adenocarcinoma (4 papers, 2004 to 2022). A common cancer characterized by the presence of malignant glandular cells. "KLK6 overexpression was reported in precancerous colorectal and duodenal adenomas and early stage adenocarcinomas with an upregulated Wnt/β-catenin pathway." (PMID 31692974, 2019). "Kallikreins are being investigated as potential serum markers for adenocarcinomas such as prostate (KLK2), breast (KLK10, 12, 13) and ovary (KLK6, 8, 10, 11)." (PMID 14760385, 2004).
infection (3 papers, 2017 to 2024). The state of being infected such as from the introduction of a foreign agent such as serum, vaccine, antigenic substance or organism. "Initially, we tested the expression of KLK6 (R80Q and S197A) 72 hours post-infection by immunoblotting." (PMID 27845893, 2017). "To evaluate whether cell-secreted KLK6 could cleave secreted α-synuclein, we transduced five day-old primary cortical neurons with adenoviruses driving the expression of constitutively active KLK6 R80Q and inactive KLK6 S197A, using 50 multiplicities of infection (MOIs) for 24 hours." (PMID 27845893, 2017).
neurological diseases (3 papers, 2020 to 2022). "KLK6 is known to be specificity enhanced in the brain and abnormally expressed in many neurological diseases, and its role in CH is still unclear." (PMID 34915845, 2021). "The findings of these studies support our conclusions and confirm that KLK6 is involved in neurological disorders." (PMID 34915845, 2021). "Evidence indicates that KLK6 is widely localized in the CNS, and its deregulation may be of relevance in a variety of neurological disorders." (PMID 32655372, 2020). "KLK6 is a member of the KLK-related peptidase family, whose members are prominent in various neurological disorders." (PMID 34915845, 2021).
colorectal (2 papers, 2021 to 2024). "Background/Objectives: The objective of this study was to assess the role of a secreted serine protease, kallikrein-related peptidase 6 (KLK6), during colorectal tumorigenesis driven by a mutant Adenomatous polyposis coli (APC) tumor suppressor gene." (PMID 39594797, 2024).
head and neck tumor (2 papers, 2015 to 2021). "Although in this study we focused on protein-coding genes, we noted top two highly up regulated non-coding transcripts in KLK6 high group samples, i.e., CTB-147C22.8 and CTB147C22, which were reported to be co-expressed with kallikrein genes KLK5, KLK6, and KLK7 in HPV16+ head and neck tumors." (PMID 34065672, 2021).
KLK6 also shares sentences with these, for which no sentence is quoted: metastatic tumors (4 papers); atopic dermatitis (2); Cognitive impairment (2); COVID-19 (2); endometrial carcinoma (2); salivary gland tumors (2); amyotrophic lateral sclerosis (1); benign tumors (1); bladder tumor (1); brain injury (1); cardiovascular disease (1); clear cell carcinoma (1); CNS tumor (1); demyelinating disease (1); demyelination (1); endometriosis (1); ependymoma (1); esophageal adenocarcinoma (1); gastric ulcer (1); glottis cancer (1); hepatocellular carcinoma (1); Hydrocephalus (1); in situ adenocarcinoma (1); inflammatory skin disease (1); injury (1); ischemia (1); ischemic stroke (1); joint diseases (1); Knee Osteoarthritis (1); Lewis lung carcinoma (1).
A further 22 diseases each share a sentence with KLK6 in 1 paper.